ARID1A (AT-rich interaction domain 1A)
Diseases named in the same sentence as ARID1A in open-access papers (continued):
Sharing a sentence is not in itself a finding about the gene and the disease.
cancer (continued). "Mutations in these genes appear to be either specific to ICC, as is the case of IDH1 and IDH2 (p=0.0005), or cluster within this cancer type as is the case for ARID1A, BAP1, and PBRM1 that were found in 34.3% (24/70) of ICC." (PMID 24867389, 2014). "Two important SWI/SNF complexes implicated in cancer are the BAF and PBAF complexes, which contain the mutually exclusive ARID1A or ARID1B subunits and PBRM1 or BRD7 subunits, respectively." (PMID 24622842, 2014). "As a comparison, only five known cancer genes that are mutated in >10 cancer types (NF1, EP300, BRCA2, MLL, ARID1A) are longer than 4,450 bp." (PMID 23718799, 2013). "Molecular mechanisms for low ARID1A mRNA and protein expression appear to be different among various types of malignant tumors." (PMID 23349767, 2013). "Whilst there is fast growing knowledge about the distribution of mutations of ARID1A and other members of the SWI/SNF complex in various cancers, functional and clinic-pathological data remain quite sparse." (PMID 24036443, 2013). "Various studies have looked at ARID1A’s effect on different cancer types." (PMID 40429787, 2025). "Thus, understanding the role of ARID1A opens a new path for advanced treatment approaches in cancer biology." (PMID 41514650, 2025). "Given the role of ARID1A in chromatin remodeling, drugs that target epigenetic regulators, such as histone deacetylase (HDAC) inhibitors or DNA methyltransferase inhibitors, may offer therapeutic benefits to patients with ARID1A-mutant cancers." (PMID 40072110, 2025). "Additionally, ARID1A deficiency is associated with a reduced mismatch repair (MMR) capacity and increased cancer mutability to recruit infiltrating immune cells, increasing the therapeutic efficacy of ICBs." (PMID 40750787, 2025). "ARID1A, a subunit of the BAF chromatin remodeler, is frequently mutated in cancer." (PMID 40938753, 2025). "Interestingly, studies have identified that ARID1A deletion has a dual role in promoting cancer and enhancing immune responses." (PMID 40342423, 2025). "This work finds that ARID1A is a critical regulator of inflammatory signaling in NB and provides rationale for testing immune therapies in MYCN amplified NB that are effective in adult ARID1A mutated cancers." (PMID 40082458, 2025). "In the Cancer Genome Atlas-Stomach Adenocarcinoma (TCGA-STAD), an immune-related risk model (ARM) was constructed based on differentially expressed immune genes associated with ARID1A mutations." (PMID 40406134, 2025). "ARID1A mutations are found in approximately 30–50% of ECs and are associated with loss of function of the SWI/SNF chromatin remodeling complex, which leads to altered gene expression and contributes to cancer development." (PMID 39858102, 2025). "Strategies to target cancers with ARID1A and KDM6A deficiency are not as mature as those targeting the PI3K/AKT/mTOR pathway; however, several recent promising results have been reported, offering hope for future research." (PMID 40723241, 2025). "Because of ARID1A’s canonical role in chromatin remodeling, it is no surprise that genomic instability is the most commonly featured cancer hallmark." (PMID 40429787, 2025). "In addition, ARID1A, BRAF, and PIK3CA mutations seemed to increase in the metastatic cohort, compared with TCGA and in-house primary cancer cohorts (all p < 0.05)." (PMID 39941707, 2025). "Interestingly, a previous functional genome-wide shRNA screen had shown that knock-down of ARID1A rescued a variety of cancer cell lines from FASLG-induced apoptosis." (PMID 39843653, 2025). "Notably, several genes identified in our CRISPR screen, including ARID1A, PSIP1, RNF2, UBE2D and MEN1, were previously associated with chemoresistance in various cancer types, reinforcing the biological relevance of our findings." (PMID 40583060, 2025).
cancer (continued). "This demonstrates that loss of function mutations of the ARID1A gene itself is not the only way to achieve the cancer hallmark of cellular plasticity." (PMID 40429787, 2025). "Extended from the study, ARID1A‐deficient cancer cells were found to be susceptible to Ataxia‐telangiectasia and rad3‐related protein kinase (ATR) inhibitors because these cancer cells show defects in topoisomerase 2A and cell cycle regulation, leading to a dependency in ATR function." (PMID 40621620, 2025). "ARID1A’s role as a global regulator of chromatin structure underpins the diverse effects of the disruption of this gene, which complicates the study of its role in cancer development." (PMID 40761291, 2025). "This indicates the role of ARID1A expression in primary cancer in various types of tumors." (PMID 39796161, 2025). "Notably, ARID1A has a mutually exclusive paralog subunit, ARID1B, which was identified as a major vulnerability in ARID1A-deficient cancer cell lines, suggesting that ARID1B is a therapeutic target in ARID1A-deficient cancers." (PMID 41017120, 2025). "Low ARID1A expression cancer patients may benefit from a combination of radiation therapy and DNA damage repair inhibitors to increase DNA damage load and/or immunotherapy to further enhance the function and infiltration of immune cells." (PMID 39779467, 2025). "Co-occurrence of ARID1A and PIK3CA mutations are frequently observed in various cancers." (PMID 40761291, 2025). "Similarly, the research "KLF5 loss sensitizes cells to ATR inhibition and is synthetic lethal with ARID1A deficiency" published on January 8, 2025, highlighted the potential of targeting the KLF5-ARID1A axis in cancer cells." (PMID 41542076, 2025). "In metastatic urothelial carcinoma, mutations in the ARID1A gene and increased expression of C‐X‐C motif chemokine ligand 13 (CXCL13) in cancer tissue improve sensitivity to immune checkpoint therapy; both can serve as biomarkers predicting efficacy of such therapy." (PMID 39779467, 2025). "Co-occurring ARID1A deficiency and PI3KA mutations are observed in ~6% of all cancer cases." (PMID 41514650, 2025). "ARID1A-mutant cancers, particularly those with upregulated PI3K/AKT signaling, may respond to targeted therapies that inhibit this pathway." (PMID 40072110, 2025). "ARID1A mutations are often associated more with cancer disease progression, rather than disease onset." (PMID 40429787, 2025). "The impairment of homologous recombination due to ARID1A loss suggests that PARP inhibitors, which target single-strand DNA break repair, may be effective against ARID1A-mutant cancers." (PMID 40072110, 2025). "Targeting the ATR/CHK1 axis triggers cancer cell-intrinsic innate immunity via the STING-mediated DNA-sensing pathway, thereby enhancing the therapeutic efficacy of radiotherapy (RT) and ICBs in ARID1A-deficient tumors." (PMID 40750787, 2025). "The loss of ARID1A results in the destruction of the SWI/SNF complex, leading to an imbalance of genes expression in cell stemness, and cell differentiation, and promotes the growth of cancer." (PMID 39928247, 2025). "This suggests that treatments targeting these vulnerabilities could be useful in counteracting low ARID1A expression and its effect on the cell cycle in cancer cells." (PMID 40429787, 2025). "In addition, since ARID1A was predicted as a potential target gene for miR-129-5p and miR-3613-3p, we conducted experiments on cancer cell lines to validate this regulation in vitro." (PMID 39796161, 2025). "Alterations in ARID1A are significantly associated with more prolonged progression-free survival (PFS) after immune checkpoint inhibition in various human cancers, independent of TMB or MSI status." (PMID 39697230, 2024). "An in-depth study of the function of the ARID1A gene and its specific molecular mechanism of action will help to increase the understanding of the biological role of chromatin remodeling complexes and provide new ideas for cancer diagnosis and treatment." (PMID 39697230, 2024).
cancer (continued). "The identification of novel somatic variants, particularly in genes like ARID1A and MLH1, which play critical roles in chromatin remodeling and DNA mismatch repair, respectively, further emphasizes the need for personalized approaches in cancer treatment." (PMID 39296440, 2024). "However, resistance to EZH2 inhibitors are observed in ARID1A mutant cancers and recent data suggest that the switch of the SWI/SNF catalytic subunits from SMARCA4 to SMARCA2 underlies the acquired resistance to EZH2 inhibitors." (PMID 39471843, 2024). "ARID1A is a critical component of the SWI/SNF chromatin remodeling complex, which modulates the accessibility of DNA to transcription and repair machinery and is frequently mutated in cancers." (PMID 37934611, 2024). "The protein BAF250A encoded by the ARID1A gene is one of the essential subunits of the SWI/SNF chromatin remodeling complex, and in a wide range of tumors, ARID1A is the most commonly mutated subunit in the SWI/SNF complex and one of the most commonly mutated oncogenes in human cancers." (PMID 39697230, 2024). "Targeting ARID1A mutations directly for therapeutic purposes is not feasible, thus driving the investigation of the synthetic lethality strategy to target cancers with ARID1A deficiency." (PMID 38610698, 2024). "Cancer patients with low ARID1A expression would benefit and respond better to the combination of radiotherapy either with DDR inhibitors (DDRi) to increase the load of DNA damage, and/or with immunotherapy to further enhance the functions and the infiltration of immune cells." (PMID 38587186, 2024). "While progress is being made with monotherapies, combination immune therapies with immune checkpoint inhibitors are also being studied for use with mSWI/SNF mutations, particularly with ARID2, polybromo 1 (PBRM1), ARID1A, and SMARC1B in cancer (Mittal and Roberts 2020)." (PMID 38914477, 2024). "Interestingly, recurrent mutations of ARID1A and NOTCH1 have been frequently associated with many types of cancer." (PMID 38043798, 2024). "Therefore, an in vivo screening of several DDRi combined with Radio- and immunotherapy in ARID1A-depleted tumors will have a translational impact as it will provide potential therapeutic approaches to improve cancer treatment." (PMID 38587186, 2024). "Correlations between ARID1A expression and prognosis have been reported for various carcinomas." (PMID 38893118, 2024). "Given the crucial role of ARID1A in multiple tissue types, it is not surprising to see that mutations of ARID1A have emerged in a broad range of cancers of different origins." (PMID 36980292, 2023). "Conversely, the restoration of ARID1A inhibits the proliferation of these cancer cells." (PMID 38041544, 2023). "assessed the clinicopathological correlation and prognostic significance of ARID1A expression by an immunohistochemical study: they proved that low level of ARID1A was significantly correlated with higher nuclear grade, advanced pTNM stage, and shorter cancer-specific and progression-free survival." (PMID 36890819, 2023).
cancer (continued). "Given the emerging roles of ARID1A in the DNA damage response, accumulating evidence has enhanced our understanding of the biological role of ARID1A, offering new mechanisms for synthetic lethality-based targeting of ARID1A-inactivated cancers, such as inhibition of PARP and ATR." (PMID 36980292, 2023). "Thus, the expression or function of ARID1A and ARID4B genes seem to have opposite associations in cancer development." (PMID 38137006, 2023). "The most frequent genomic alteration in the “MSI-H” group was ARID1A in all three cancer types." (PMID 38201563, 2023). "1p36 (ARID1A): Although not implicated for this syndrome in studies so far, ARID1A is located in 1p36.11, a region frequently deleted in human cancers." (PMID 37372241, 2023). "ARID1A is being configured as a potential new target for cancer treatments." (PMID 37711591, 2023). "Given the central role MSH-2 plays in detecting and initiating MMR, this may explain the requirement for ARID1A in MMR and the higher prevalence of ARID1A deficiency in dMMR cancers." (PMID 38275587, 2023). "Interestingly, the involvement of ARID1A in cancer is transposed as a putative mechanism to explain the brain malformations associated to CSS." (PMID 36859317, 2023). "Therefore, several clinical trials are underway in patients with ARID1A mutant cancers with inhibitors of ATR and PARP (ClinicalTrials.gov Identifiers NCT03207347, NCT04042831, NCT02576444, NCT04065269)." (PMID 37093326, 2023). "It was reported that ARID1A suppressed histone deacetylase 6 (HDAC6) in OCCC directly, and HDAC6 nuclear expression was associated with immuno- and hypoxia tolerance and cancer stem cell phenotype in OCCC and upregulated following chemotherapy, leading to a poor prognosis." (PMID 36873929, 2023). "However, new evidence suggests a crucial role of some gene mutations (PTEN, PIK3CA, FGFR2, ARID1A, and MYC) in cancer progression from endometrial hyperplasia." (PMID 38201599, 2023). "Based on this regulatory link, the modulation of ARID1A expression or function could be a promising strategy for treating YAP-driven cancers." (PMID 37173914, 2023). "The ARID1A gene produces a subunit of the ATP-dependent histone deacetylase SWI/SNF complex that has been implicated in developmental disorders, as well as 20% of all cancers therefore potentially an important synthetic lethal gene dependency target for iPSCs." (PMID 37028423, 2023). "As mentioned, if we could break the new redox balance in ARID1A mutant cancer cells, therapeutic effects could be achieved." (PMID 37238613, 2023). "Rationalizing that this known SL interaction and complex association would serve as positive controls, we applied GRETTA to predict pan-cancer GIs and essentiality networks of ARID1A, expecting to replicate known interactors and co-essential genes, respectively." (PMID 37326978, 2023). "Furthermore, the inactivating mutation of ARID1A also reactivates the repressed TERT transcriptional activity and renders growth advantage to cancer cells." (PMID 37371564, 2023). "Since ARID1A mutation cells induce upregulation of ATR, blocking ATR activity could work as an ICC treatment by reducing cancer cell survival." (PMID 38203635, 2023). "Our results thus confirm the sensitivity of ARID1A mutant cancer lines to proteotoxic stress, which could be therapeutically exploited." (PMID 37028423, 2023). "ARID1A alterations are quite common among cancer patients, although their role remains debated." (PMID 37711591, 2023). "In cancers, ARID1A deletion promotes STING-mediated innate immune responses." (PMID 38139802, 2023). "The authors hypothesized that epithelial cells with ARID1A loss can be more easily infected by EBV and this could lately trigger cancer development." (PMID 36890819, 2023).
cancer (continued). "This gene set contained well-known cancer driver genes ARID1A, PTEN, PIK3CA, and CTNNB1." (PMID 37444632, 2023). "With these synergistic mechanisms, this system could effectively inhibit cancer cell proliferation and contribute to treating ARID1A mutant OCCCs." (PMID 37238613, 2023). "Indeed, the impact of ARID1A inactivation extends beyond GC and is observed in various other types of cancer as well." (PMID 38041544, 2023). "Given the rapid emergence of resistance to monotherapy in cancer, we investigated whether combination BRD4i with WEE1 or ATR inhibition would be a strategy to exploit ARID1A loss by targeting two critical pathways critical for survival." (PMID 37841875, 2023). "ARID1A-low group had significantly lower DUSP4 expression (p = 0.0125) in carcinoma tissues." (PMID 38071325, 2023). "Interestingly, accumulating evidence indicates that epigenetic modifications such as DNA hypermethylation and histone modifications play significant roles in ARID1A gene downregulation in cancer." (PMID 35611248, 2022). "Hence, ATR inhibitors are likely to present a synthetic lethal strategy to target cancer cells with mutant or low ARID1A expression." (PMID 36249060, 2022). "An expanded study is needed to further confirm the role of ARID1A in cancer immunotherapy." (PMID 36229854, 2022). "In addition, we previously uncovered in a two-hybrid screen an association between TASOR and ARID1A, a SWI/SNF subunit gene that is very frequently mutated in cancers." (PMID 36309692, 2022). "Indeed, depleting cancer cells of ARID1A using CRISPR-Cas9 technology or by infecting ARID1A wild-type cells with VSVΔ51-amiR-4 renders these cells significantly more sensitive to infection and virus-mediated killing." (PMID 35393414, 2022). "These genes include ARID1A, a tumor suppressor and chromatin regulator and LRP1B, which encodes a low-density lipoprotein receptor-related protein that is frequently mutated in cancers." (PMID 35557512, 2022). "Additionally, retrospective studies have reported relationships between ARID1A mutations and mutational load and with the immune environment, implying a clinical benefit from ICI in cancers harboring ARID1A mutations." (PMID 34042312, 2022). "The SWI/SNF genes, ARID1A, ARID1B, ARID2, SMARCA4, SMARCB1, and PBRM1 were mutated in up to 21.8% of all the cancers, and SWI/SNF mutation carriers had significantly higher TMB values as well as higher TMB-H and MSI-H proportions than their SWI/SNF-non-mutant counterparts in several malignancies." (PMID 36371186, 2022). "However, during mitosis, ARID1A deficiency results in cohesion protein STAG1 downregulation, and cancer cells with chromosome aberrations are eliminated during mitosis due to telomere cohesion deficiency." (PMID 36430148, 2022). "AT-rich interactive domain 1A (ARID1A), aurora kinase B (Aurora-B), α-thalassemia/mental retardation syndrome X-linked (ATRX), and baculoviral IAP repeat-containing 5 (BIRC5) are also among the genes involved in cancer drug resistance." (PMID 35715750, 2022). "BRD2 inhibitors reduce ARID1B and other SWI/SNF member expression in ARID1A mutant cancers." (PMID 36430148, 2022).